CRH (corticotropin releasing hormone)
Diseases named in the same sentence as CRH in open-access papers (continued):
Sharing a sentence is not in itself a finding about the gene and the disease.
Anxiety (continued). "Understanding the role of the CRH system in mediating fear processing and anxiety- and stress-related behaviors in psychiatric disorders such as PTSD may provide us with potential methods of pharmacological intervention to reverse these maladaptive processes." (PMID 39595978, 2024). "Moreover, selective deletion of the GABAA α1 subunit gene in the CRH neurons of mice produces a phenotype with increased anxiety as well as impaired fear memory extinction, both of which are hallmarks of PTSD." (PMID 37097603, 2023). "Furthermore, ACE2 downregulation in the hypothalamus induces stress and anxiety responses by increasing corticotropin-releasing hormone." (PMID 37575318, 2023). "Notably, CRH peptidergic neurons in the amygdala are activated by glucocorticoids and upon activation, lead to the stimulation of the stress circuitry and fear/anxiety." (PMID 37425005, 2023). "PVH neurons, in addition to the well-studied CRH neurons, contain other types of neurons that send projections to the lateral septum (LS), a known brain region involved in aggression and anxiety, to inhibit feeding while promoting anxiety-like behaviors and reducing aggression." (PMID 33826123, 2022). "However, in stress-related diseases such as depression and anxiety, CRH is secreted excessively, hyper-activating the HPA axis and causing a detrimental physiologic state." (PMID 35275963, 2022). "CRH also stimulates the amygdala, which is a key brain area for fear and anxiety." (PMID 35903448, 2022). "In some cases, CRH or TACP receptor antagonists have different effects on anxiety, based on the animal test line, the baseline of depression, or perceived anxiety or the treatment regimen, but also depending on the test, as these therapeutics do not work under basal conditions." (PMID 36004833, 2022). "This suggests local positive feedback of CRH production of hypothalamic neurons, which may lead to increased anxiety." (PMID 36275850, 2022). "In addition, we also analyzed the effects on the mRNA expression of other signaling systems related to anxiety and stress (e.g., CRH and neuropeptide Y (NPY)) in the amygdala of young male adult rats." (PMID 35327395, 2022). "Only two studies investigated HPA axis responsiveness with in vivo 5-HTT availability by means of [11C]DASB, either in healthy volunteers applying the cortisol awakening response (CAR) or in patients with major depression or anxiety disease using the dexamethasone CRH test." (PMID 36358358, 2022). "Muscle mitochondrial stress signals to the brain via hindbrain-specific GFRAL receptor signaling to promote hypothalamic CRH induction, which associates with GFRAL-dependent modulation of systemic energy metabolism, diurnal food intake, and anxiety-like behavior." (PMID 36271504, 2022). "Moreover, the ARA metabolite is also the precursor of endocannabinoid (eCB), and eCB affects anxiety-like behavior by activating the endocannabinoid system and regulating neurotransmitters, CRH in the HPA axis, and the dopaminergic reward system in the brain." (PMID 35624976, 2022). "Previous research indicates that corticotropin-releasing hormone (CRH) neurons are modulated by neurosteroid tetrahydro-deoxycorticosterone (THDOC) and act on GABAAR-containing δ subunits which share close associations with anxiety-like behaviors." (PMID 36287173, 2022). "Additionally, a study on the consequences of chronic stress on PACAP expression in the bed nucleus goes in hand with CRH, indicating that synergic modulation exists in anxiety-like behavior." (PMID 36004833, 2022). "CRH is associated with anxiety and arousal, has a nonlinear effect on behavior when acting among multiple receptors, and is associated with psychiatric disorders, including depression." (PMID 34997033, 2022). "Moreover, data confirmed CRH pathway as a potential entry point for the treatment of anxiety in RTT and related conditions." (PMID 34895132, 2021).
Anxiety (continued). "The function of sgPFC (subgenual PFC) – a term used interchangeably with subgenual anterior cingulate cortex (sgACC) – is moderately diminished during normal stress to disinhibit the CRH and the LC-NE systems and consequently to promote anxiety and arousal, while diminishing appetite and sleep." (PMID 34177605, 2021). "Disturbancesof the CRH system regulation are directly related to such disorders: mental pathologies (depression, anxiety, addictions), deviations of neuroendocrinological functions, inflammation, as well as the onset and development ofneurodegenerative diseases such as Alzheimer’s disease." (PMID 34901719, 2021). "This demonstrates the importance of BST CRH neuron activation in areas beyond the regulation of anxiety-like behavior, and CRHR1 antagonists remain a potential avenue for the development of therapeutics that help prevent the reinstatement of drug-seeking behavior." (PMID 33867924, 2021). "BST CRH neurons are concentrated in the BSTov, which is critical for the regulation of anxiety states and may have a role as the master controller of the BST." (PMID 33867924, 2021). "Pituitary adenylate cyclase–activating polypeptide (PACAP), operating through the Gs/Gq protein–coupled PAC1 receptor (PAC1R), is an upstream regulator of CRH that innervates CRH neurons in the BSTov, where it contributes to increased anxiety states and can activate the HPA axis." (PMID 33867924, 2021). "Therefore, possible changes in anxiety were evaluated in CRH GHR KO mice during the open field and elevated plus maze tests." (PMID 34576072, 2021). "Anxiety is controlled by CRH neurons in the PVH, CEA and BNST." (PMID 34576072, 2021). "Given that CRH primes both mechanisms, this might provide a mechanism for reinforcement of anxiety, fear learning and a bias for passive responding." (PMID 29904149, 2020). "Furthermore, it has been shown that CRH overproduction in transgenic unstressed mice resulted in increased anxiety-like behavior." (PMID 33304248, 2020). "Its upregulation in young MPS males and females may indicate reduced CRH expression contributing to higher anxiety-like behaviour, a consequence of reprogrammed endocrine system activity by ancestral experience." (PMID 32087063, 2020). "In addition, the CE is rich in various neuropeptides capable of modulating anxiety levels (e.g., enkephalin, neuropeptide Y and CRH)." (PMID 29904149, 2020). "Moreover, interesting studies showed that maternal cortisol, CRH and the State-Trait Anxiety Inventory (STAI) score significantly increased from 2nd to 3rd trimester." (PMID 32758184, 2020). "Taken together, our findings are along with the hypothesis that while OXT is primarily engaged in the performance of social behaviors, CRH is greatly involved in the regulation of stress and anxiety." (PMID 30898126, 2019). "All the results suggested that EA and MB at the ST36 and CV4 acupoints could increase the CRH protein expression in the colon to effectively relieve anxiety behavior in DSS-induced colitis model mice." (PMID 30881446, 2019). "Moreover, clinical studies have found that anxiety scores and the plasma CRH levels are significantly increased in patients with posttraumatic stress disorder." (PMID 30881446, 2019). "In order to determine whether the effectiveness of EA and MB improvement alleviates anxiety in colitis model mice linked to the “HPA axis,” we had measured serum levels of CRH and CORT in the various groups by means of ELISA." (PMID 30881446, 2019). "In response to stress, hypothalamic and extrahypothalamic CRH is released and binds to CRHR1 in the LC, causing a more tonic phase in these cells and consequential NE release, increased vigilance, hyperarousal and anxiety." (PMID 30804766, 2019). "It has been demonstrated that dysregulations of the CRH-HPA axis system may contribute to pathological anxiety." (PMID 30881446, 2019).
Anxiety (continued). "In order to address this question, we assessed whether conditional deletion of CRH from forebrain GABAergic neurons (CrhCKO–GABA mice) would differently affect anxiety, social behavioral and cognitive parameters under baseline and chronic stress conditions." (PMID 31619956, 2019). "However, few studies to date implicate the CRH or their receptors alleviating anxiety behavior in DSS-induced colitis." (PMID 30881446, 2019). "Finally, we present work unravelling a new role for hypothalamic corticotropin-releasing hormone (CRH) neurons in controlling anxiety-like and stress-induce behaviors." (PMID 31467945, 2019). "All the results suggested that EA and MB at the ST36 and CV4 acupoints could increase the CRH protein expression in the colon and effectively relieve anxiety behavior in DSS-induced colitis model mice." (PMID 30881446, 2019). "Although it is well established that CRH/CRHR1 signaling mediates aversive responses, including anxiety and depression-like behaviors, several recent studies have challenged this viewpoint by revealing anxiolytic and appetitive properties of specific CRH/CRHR1 circuits." (PMID 31619956, 2019). "Interestingly, many Lef1-dependent genes in zebrafish encoding components of anxiety-mediating transmitter pathways, such as GABA, 5-HT, and CRH, have a conserved function in Drosophila anxiety-like behavior." (PMID 28837622, 2017). "CRH-BP modulation of CRH-R1 activity on pyramidal neurons may mediate anxiety-like behavior, as conditional knockdown of CRH-BP in oxytocin receptor interneurons in the mPFC increased anxiety in male (but not female) mice." (PMID 29066956, 2017). "Chronic variable stress in the third week of pregnancy in rats leads to increased anxiety-like behavior in the elevated-plus-maze (EPM) in young adult offspring and is associated with increased CRH and CRHR1 in the amygdala of female offspring and CRHR2 expression in offspring of both sexes." (PMID 26082698, 2015). "Altered expressions of glucocorticoid receptors and corticotropin-releasing hormone (CRH) in the hippocampus and amygdala have been reported to result from prenatal stress and may be related to increased anxiety and depression-related behavior." (PMID 24574956, 2014). "One hypothesis is that CRH in the amygdala is tied more specifically to fear and CRH in the bed nucleus to anxiety." (PMID 23913254, 2014). "Moreover, deletion of GABA-A α1 receptor subunit in CRH neurons was shown to lead to increased CRH expression in the amygdala and to increase anxiety-like behavior." (PMID 24736324, 2014). "High CRH levels occur in adults who have been exposed to violence as children, and this chronic elevation leads to arousal, anxiety, aggression, hypervigilance, general sympathetic nervous system stimulation, depression, and problems with eating and sex, i.e., symptoms of PTSD and depression." (PMID 25346927, 2014). "In a separate study, short-term inducible CeA CRH overexpression increased anxiety after stress." (PMID 23077729, 2012). "Negative strain, stressors, cause negative affective states, e.g. anxiety, that alter the production of Corticotropin-Releasing Hormone (CRH) in the paraventricular nucleus of the hypothalamus." (PMID 22026917, 2011). "Prenatal glucocorticoid exposure increases adult CRH levels specifically in the central nucleus of the amygdala and therefore may be responsible for the increase in anxiety-like behaviour observed in these animals." (PMID 21144857, 2011). "This hypothesis is supported by findings that administration of a CRH antagonist outside the hypothalamus can reverse withdrawal-induced anxiety." (PMID 15706797, 1998). "Increased CRH release in that nucleus has an anxiety-inducing effect." (PMID 15706797, 1998).
Anxiety (continued). "We believe that a better understanding of the role of the CRH system in fear processing and anxiety- and stress-related behavior in psychiatric disorders such as PTSD may pave the way for the use of pharmacological interventions to target the mechanisms leading to the development of PTSD pathology." (PMID 39595978, 2024). "Anxiety and stress may lead to the activation of corticotropin-releasing hormone (CRH)." (PMID 38406089, 2024). "Furthermore, the CRH system plays a role in psychopathology, anxiety, and depressive disorders triggered by prolonged chronic stress, and various neuro-behavioral-endocrine-sympathetic-immune responses intensely involve the CRH system." (PMID 38927393, 2024). "In conclusion, moderate CKD evoked anxiety-like behavior that might be mediated by the accumulation of uremic toxins and metabolites of the kynurenine pathway, but the contribution of the amygdalar CRH system to the development of anxiety seems to be negligible at this stage." (PMID 37989901, 2024). "In addition, disturbances of the CRH system regulation could be related to many disorders, such as depression, anxiety, and inflammatory bowel diseases." (PMID 37358267, 2023). "Finally, mRNA levels were measured in female rats that had prior exposure to anxiety-eliciting tasks so whether similar patterns in CRH and GABAAR subunit expression are evident at baseline in experimentally naïve animals is unknown." (PMID 37253788, 2023). "In addition, a direct, HPA-axis-independent involvement of CRH in mood disorders has long been hypothesized based on the finding that central CRH signaling is responsible for anxiety-like behavior." (PMID 36552294, 2022). "CRHR2 down-regulation may also lead to hypercortisolemia via an inappropriately high-normal CRH and ACTH, via CRHR1 pituitary activation, and simultaneously drive central and peripheral catecholamine secretion, which can further mediate the anxiety-causing and hyperglycemic effects." (PMID 36077219, 2022). "Moreover, a number of studies have shown similar effects of aerobic training, which decreases cortisol concentration, normalizes serotonergic and noradrenergic concentration and corrects the release of corticotropin-releasing hormone, and in turn modulates the responsiveness to anxiety and stress." (PMID 36329786, 2022). "In addition, serum CRH levels positively correlated with depression and anxiety." (PMID 35508633, 2022). "It is possible that upregulation of CRH neurons in the BST and subsequent activation of HCRT-LH neurons may therefore contribute to the increased arousal states associated with anxiety and other altered mood states, as well as contribute to the role of the BST in regulating addiction." (PMID 33867924, 2021). "Interestingly, corticotropin-releasing hormone (CRH), as a major integrator of the stress response, was also shown to activate the NE-LC system and to promote tPA activity in the amygdala to elicit subsequent anxiety-related behavioral effects." (PMID 33510345, 2021). "Pathologies such as anxiety and affective disorderscaused by an increased glucocorticoids level and disordersin the functioning of the brain neurotransmitter systems maybe due to an increased CRH expression in CeA and BNST." (PMID 34901719, 2021). "According to the present investigation, this mainly involves IL-1β, CRH, and dopamine (and to a lesser extent serotonin) which could influence the synbiotic-induced reduction in perceived levels of anxiety and stress, fatigue and depression, as well as the objective improvement in sleep quality." (PMID 33923663, 2021). "Hyperactivity of the HPA axis in an anxiety state may result from hypersecretion of CRH." (PMID 30881446, 2019).
Anxiety (continued). "Similarly to anti-OT IgG, plasma levels of AVP-reactive IgG correlated with symptoms of anxiety and somatization and that the levels of CRH-reactive IgG in plasma of healthy subjects correlate positively with obsessive or hypochondriac behavior, but negatively (as anti-AVP IgG) with somatization." (PMID 31866881, 2019). "Co-expression with fear-associated genes Crh, Crhr1, and Crhr2 across crude brain regions revealed that the metabolic receptor set correlated mostly in areas that are not often associated with anxiety, i.e., midbrain CRH expressing neurons, as present in the superior colliculus and nucleus ruber." (PMID 30210279, 2018). "Also, for individuals with altered NPYergic system, enhancing NPY levels and function may help to improve stress and anxiety regulation and to minimize the anxiogenic effects of CRH." (PMID 23422934, 2013). "CRH is also distributed in the extra-hypothalamic region including the amygdala and the bed nucleus of the stria terminalis (BNST), both of which are closely associated with fear and anxiety, suggesting that CRH mediates the behavior in unfamiliar surroundings." (PMID 19787076, 2008). "Downregulation of ASIC1a in the PVN CRH neuron decreased the hypothalamic-pituitary-adrenal (HPA) axis activity, which further ameliorated anxiety- and depression-related behaviors by reducing CRH neuron activity." (PMID 41856976, 2026). "Chronic stress triggers prolonged activation of the HPA axis, elevating levels of corticotropin-releasing hormone (CRH) and cortisol, central mediators in the pathophysiology of depression and anxiety." (PMID 41226736, 2025). "For instance, yohimbine-induced increases in NE and CRH release in the BNST and amygdala increases neuronal firing in the LHb, correlating with the expression of anxiety-like behaviors." (PMID 40635883, 2025). "Corticotropin-releasing hormone (CRH) and its receptor, CRHR1, are known to be involved in the regulation of anxiety." (PMID 40243462, 2025). "The CRH/CRHR1 system is involved in stress responses, and an imbalance in CRHR1 expression can lead to heightened anxiety and stress reactivity." (PMID 40243462, 2025). "Inhibiting this group of CRH neurons or pharmacologically blocking their receptor (CRHR1), markedly enhanced the excitability of layer V mPFC neurons and improved anxiety and depressive-like behaviors in chronic pain mice." (PMID 39859152, 2025). "For instance, corticotropin-releasing hormone (CRH) overexpression and CRH receptor knockouts delineate the distinct roles of these receptors in mediating anxiety and stress responses." (PMID 39728686, 2024). "CRHR2 is one of the receptors through which corticotropin-releasing hormone (CRH) acts to regulate stress responses and plays an important role in the development of anxiety and depression." (PMID 39684893, 2024). "CRH, secreted by parvocellular neurons in the PVN, acts as the “gatekeeper” for initiating HPA axis and is a significant factor contributing to anxiety." (PMID 39153974, 2024). "The ovBNST plays a crucial role in integrating information related to negative emotional stimuli through neurotransmitters such as corticotropin-releasing hormone (CRH), GABA, dopamine (DA), and dynorphin, thereby influencing anxiety-like behavior." (PMID 39698215, 2024). "Alenina and Bader reported that ACE2 overexpression in the hypothalamus inhibits corticotropin-releasing hormone synthesis and consequently decreases POMC and corticosterone release, which in turn suppresses the stress response and anxiety." (PMID 37575318, 2023). "Wang and co-authors identified that directing the overexpression of ACE2 to CRH cells attenuates stress-induced HPA axis activation and anxiety-like behavior and decreased the expression of CRH mRNA in the PVN and central nucleus of the amygdala (CeA)." (PMID 37638323, 2023). "Under chronic stress, the CRH continues to be released and the HPA axis is disordered; then, the anxiety and depression behavior increase." (PMID 36831854, 2023).